FLT1 (fms related receptor tyrosine kinase 1)
Diseases named in the same sentence as FLT1 in open-access papers (continued):
Sharing a sentence is not in itself a finding about the gene and the disease.
breast carcinoma (continued). "Using new mouse models of PARPi response and recurrence, we identified FLT1 as a potential biomarker and therapeutic target for reversing PARPi resistance in BRCA-mutant breast cancer." (PMID 38956205, 2024). "The tumor microenvironment (TME) of HR+/HER2- breast cancer cells is composed of CD3D+ T cells, CD68+ macrophages, COL1A1+ fibroblasts, and FLT1+ endothelial cells." (PMID 38892065, 2024). "Our study therefore identifies FLT1 as a potential therapeutic target in PARPi-resistant, BRCA1/2-mutant breast cancer." (PMID 38956205, 2024). "Instead, agents that disrupt the PGF/FLT1/AKT pathway, such as the pan-VEGFR inhibitor axitinib, are more likely to be effective at re-sensitizing PARPi-resistant breast cancers to PARPi." (PMID 38956205, 2024). "Lenvatinib (E7080; Lenvima ®) is an oral ATP-competitive MKI with activity against FLT-1, FLT-4, KIT, FGFR1, PDGFR, VEGFR1-3, and can inhibit angiogenesis and growth of SCLC and breast cancer cells in vitro and in vivo." (PMID 35957881, 2022). "Hypoxia correlated with the proliferation rate and biologic aggressiveness of breast cancer as indicated by immunohistochemistry expression and distribution of common markers of hypoxia (HIF-1alpha, VEGF-C, CA IX, and FLT-1)." (PMID 32721996, 2020). "We observed that hypoxia correlated with the proliferation rate and breast cancer aggressiveness as indicated by immunohistochemistry expression and the distribution of common markers of hypoxia (HIF-1alpha, VEGF-C, CA IX, FLT-1, and MVD)." (PMID 32721996, 2020). "Current data suggests that KDM2A works in conjunction with E2F1 to affect FLT-1 and KDR expression in endothelial cells and MMP expression in breast cancer cells." (PMID 25029110, 2014). "Production of vascular endothelial growth factor (VEGF) and expression of its receptors Flt-1 and KDR was determined in primary cultures of separated epithelial and stromal-enriched cultures derived from ten primary human breast carcinomas." (PMID 10360672, 1999). "Notably, the FLT1-targeted drug FAMITINIB was entering phase I/II trials for various cancers, including NSCLC, breast cancer, colorectal cancer, renal cell cancer, and others." (PMID 38576019, 2024). "Breast cancer epithelial cells and stromal cells produce VEGF and express the VEGF receptors Flt-1 and KDR, indicating that VEGF can play a role not only in angiogenesis but also as an autocrine/paracrine regulator of breast cancer, thereby promoting tumor proliferation and invasion." (PMID 38516703, 2024). "FLT1 is highly expressed in breast-cancer tissues and breast-cancer cell lines, but its expression is absent or near background in normal breast tissues." (PMID 27167339, 2016). "Conversely, Flt-1 as a negative regulator of VEGF availability and thus being regarded as an antiangiogenic receptor was expressed significantly more frequently in the group of coexistent breast carcinomas." (PMID 15841074, 2005). "Initially, expression of Flt-1 and KDR was believed to be restricted to the vascular endothelium, but to date these receptors have also been detected in several types of nonendothelial cells including breast cancer cells, suggesting an autocrine effect of VEGF-A on tumour cells." (PMID 15841074, 2005).
endothelial dysfunction (76 papers, 2012 to 2026). In vascular diseases, endothelial dysfunction is a systemic pathological state of the endothelium (the inner lining of blood vessels) and can be broadly defined as an imbalance between vasodilating and vasoconstricting substances produced by (or acting on) the endothelium. "Placental ischemia produces sFlt-1, a splice variant of Flt-1 that binds to vascular endothelial growth factor and PlGF and serves as a biochemical marker of endothelial dysfunction that inhibits angiogenesis." (PMID 41458730, 2025). "FLT-1 gene variants also raise the soluble FLT-1, which leads to endothelial dysfunction and inflammation in PE." (PMID 39861817, 2024). "In PE, additional production of Flt1 and sFlt1 which cause endothelial dysfunction and anti-angiogenic state are likely related to placental hypoxia." (PMID 26221124, 2015). "Glaucoma has been associated with endothelial dysfunction and decreased levels of nitric oxide, endothelin-1 (ET-1), vascular endothelial growth factor (VEGF), and soluble VEGF receptor FLT-1." (PMID 40647700, 2025). "A high level of flt-1 was associated with the level of VEGF and severe endothelial dysfunctions, leading to severe clinical features." (PMID 36420291, 2022). "A soluble form of FLT1 is markedly increased during the last 2 months of gestation in those with PE compared with normotensive pregnant controls, which is involved in the endothelial dysfunction characterizing the pregnancy disorder of PE." (PMID 34699328, 2021). "High levels of soluble FLT1 in maternal circulation act as antiangiogenic factors and lead to endothelial dysfunction as well as end-organ dysfunction in PE." (PMID 32566660, 2020). "Fms-like tyrosine kinase-1 (Flt-1) [and/or soluble Flt-1 (sFlt-1)] and endothelin found in SDEVs are known to induce endothelial dysfunction." (PMID 31632289, 2019). "In PE excess sFlt1 binds to VEGF and PlGF and antagonizes these proangiogenic molecules resulting in preventing them to interact with their main cell surface receptors Flt1 and KDR and cause endothelial dysfunction." (PMID 26221124, 2015). "FLT-1 plays a role in angiogenesis in the placenta; elevated levels of FLT-1 may mediate maternal endothelial dysfunction, leading to hypertension." (PMID 36313546, 2022). "Thus, most clinical studies of circulating soluble Flt-1 in CKD patients has focused on endothelial dysfunction and cardiovascular diseases." (PMID 29937525, 2018). "First, excess placental soluble Flt-1 (sFlt-1) neutralises vascular endothelial growth factor (VEGF) and placental growth factor (PlGF), producing an angiogenic deficit that drives endothelial dysfunction, hypertension, proteinuria and end organ injury." (PMID 41897371, 2026). "Anti-angiogenic molecule, soluble Fms-like tyrosine kinase-1 (SFLT-1), is produced by alternative splicing of the FLT-1 gene that can be bound to VEGF and leads to endothelial dysfunction and prevent angiogenesis in placenta." (PMID 23653839, 2012). "The findings in this study do not exclude that NOVA2 could also mediate effects in the endothelium through a mechanism independent of FLT1 splicing which could further reduce endothelial dysfunction and ameliorate maternal syndrome." (PMID 35927413, 2023).
Hypertension (72 papers, 2010 to 2026). The presence of chronic increased pressure in the systemic arterial system. "Other frequently observed genes are related to eye diseases (PDE6G has been linked to Retinitis Pigmentosa, and SIX6 to glaucoma, myopia, and retinal degeneration) or vascular processes (FLT1 linked to hypertension and heart disease)." (PMID 39505872, 2024). "In conclusion, the overall genetic effect of FLT1 longevity genotypes on lifespan involves amelioration of mortality risk posed by hypertension." (PMID 37178326, 2023). "The aim of the present study was to test the hypothesis that the increased risk of death in patients with hypertension was ameliorated by longevity-associated genotypes of FLT1 SNP, rs3794396." (PMID 37178326, 2023). "In conclusion, the longevity-associated genotype of FLT1 may confer increased lifespan by protecting against mortality risk posed by hypertension." (PMID 37178326, 2023). "The present longitudinal observation study showed that the variant of FLT1 most strongly associated with longevity may confer longer lifespan by ameliorating the risk of mortality posed by having hypertension." (PMID 37178326, 2023). "In studies of FOXO3, MAP3K5, PIK3R1, GHR, and FLT1 we found that for each, the genetic variants associated with longer lifespan may activate cell resilience mechanisms, leading to amelioration of the adverse effects of hypertension." (PMID 37561089, 2023). "Belgore and coworkers’ research found elevated plasma levels of vascular endothelial growth factor (VEGF) and its soluble receptor Fms-like tyrosine kinase-1 (Flt-1) in patients with hypertension." (PMID 39684895, 2024). "In particular, FLT1 plays a role in the process of collateral vessel formation, which is a form of vascular remodeling in response to stress, such as hypoxia or hypertension." (PMID 37131961, 2023). "We suggest that FLT1 expression in individuals with longevity genotype boosts vascular endothelial resilience mechanisms to counteract hypertension-related stress in vital organs and tissues." (PMID 37178326, 2023). "NOVA2 and FLT1 expression in the placenta of PE, pregnancy-induced hypertension, and normotensive controls was measured by RT-qPCR." (PMID 35927413, 2023). "In the present study, Flt-1 overexpression in mice during placentation led to PE-like symptoms, including compromised angiogenesis in the labyrinth, and induced hypertension, kidney damage, and FGR." (PMID 35693704, 2022). "This relationship is consistent with the VIMP analysis results, where VEGFR family kinases including FLT1 (VEGFR1), VEGFR2, and FLT4 (VEGFR) have been identified as the top 1, 2, and 15 kinases associated with hypertension." (PMID 35896580, 2022). "Increased soluble flt-1 levels produces hypertension, proteinuria and glomerular endotheliosis in both pregnant and non-pregnant rats and these features also characterize pre-eclampsia." (PMID 28356151, 2017). "For the kinase MAP3K5 it was hypertension, CHD and diabetes, for the kinase receptor PIK3R1 hypertension, CHD and stroke, and for the growth hormone receptor gene (GHR) and vascular endothelial growth factor receptor 1 gene (FLT1), it was nullifying the higher mortality risk posed by hypertension." (PMID 37561089, 2023). "Effect of FLT1 genotype on mortality stratified by hypertension status." (PMID 37178326, 2023). "In cells where sFlt1 is so much more abundant than Flt1, as in the cytotrophoblast, unregulated overproduction of sFlt1 can lead to effects in distant vascular beds and both hypertension and severe proteinuria occur in experimental animals when sFlt1 is made in excess." (PMID 25387128, 2014). "Furthermore, sFLT1, a soluble Flt1 protein, is an antiangiogenic factor originating from the placenta, and its overproduction is an important event that drives the clinical features of PE, such as hypertension." (PMID 35711567, 2022).
Hypertension (continued). "Soluble FLT1 (sFLT1) is one of the VEGF inhibitors secreted by the placenta in human beings, resulting in angiogenic imbalance and high blood pressure as one of its manifestations." (PMID 37629345, 2023). "In essential hypertension, plasma levels of VEGF and sFlt-1 – the soluble form of Flt-1 – are elevated." (PMID 37178326, 2023). "We found that polymorphisms located in the FLT-1 gene do not have influence on the cardiovascular events such as coronary artery disease (CAD), hypertension (HNT) and myocarditis (MI) in patients with RA." (PMID 28323906, 2017). "Besides, longevity-promoting resilience genes like FLT1, Foxo3, GHR3, MAP3K5, PIK3R1 could mitigate mortality from hypertension, which further indicating the genetic influences in hypertension and vascular aging." (PMID 41507140, 2026).
melanoma (68 papers, 2007 to 2025). A malignant, usually aggressive tumor composed of atypical, neoplastic melanocytes. "First, we demonstrated that Vegfb or Flt1 knockout in T cells promoted the growth of the transplantable murine adenocarcinoma MC38 or melanoma B16 tumors." (PMID 39145452, 2024). "The presence of the A375 melanoma cells in the skin model led to an increased release of Flt-1 (2-fold increase), PlGF (2-fold increase), Tie-2 (1.8-fold increase), VEGF (1.8-fold increase), VEGF-C (1.7-fold increase), and VEGF-D (1.9-fold increase)." (PMID 37345186, 2023). "Increased expression of FLT1, a member of the vascular endothelial growth factor receptor (VEGFR) family, is associated with glomeruloid microvascular proliferation in malignant melanoma." (PMID 32296685, 2020). "In the midnight blue module, the hub Flt1 (fms-related tyrosine kinase 1) is a VEGF receptor that participates in the proliferation of melanoma cells, whereas Cdh5 (VE-cadherin) is highly expressed in metastatic melanoma." (PMID 32831131, 2020). "The conditioned medium from Lewis carcinoma or B16-F1 melanoma cells up-regulates the promoter activity and mRNA expression of Flt-1." (PMID 24376728, 2013). "Mutation analysis of protein tyrosine kinases identified some recurrent mutations in ERBB4 (19% of melanomas) and Fms related Tyrosine Kinase 1 (FLT1) and Protein Tyrosine Kinase 2 Beta (PTK2B) (10% of melanomas)." (PMID 29156643, 2017). "MeWo cell growth resembled the initial stages of melanoma progression without the higher secretion of immune modulatory cytokines (only a trend for M-CSF), but with higher secretion of a few pro-angiogenic factors (Flt-1 and VEGF)." (PMID 37345186, 2023).
glioma (41 papers, 2000 to 2024). A benign or malignant brain and spinal cord tumor that arises from glial cells (astrocytes, oligodendrocytes, ependymal cells). "A study by Wang and co-workers also showed that miR-139-5p inhibited the Flt1-induced Wnt/β-catenin pathway in glioma cells." (PMID 34646821, 2021). "It is known that Fms-related receptor tyrosine kinase 1 (Flt-1) signaling in myeloid cells is essential for the amplification of the angiogenic response and to promote glioma growth." (PMID 35011579, 2021). "They showed that Flt1 stimulated and miR-139-5p inhibited the proliferation of the glioma cells." (PMID 34646821, 2021). "IHC analysis of the VEGF receptor flt-1 showed strong tumour cell staining in M006XLo glioma cells." (PMID 10682677, 2000). "We further strengthened this argument by correlating the expression of the two VEGFR2 subunit genes FLT1 and KDR with the expression of EFNB2 in Glioma." (PMID 35629359, 2022). "The majority of the antineoplastic activity of honeybee venom has been attributed to melittin through inhibition of VEGF, FLT-1, and MMP-9 in glioma C6 cells; metaloprotease-2 in human glioblastoma cells; and STAT3 and VEGF in glioma SHG44 cell." (PMID 39281062, 2022). "VEGF and its receptors Flt1 (VEGFR1) and Flk1 (VEGFR2) are important proteins in the angiogenic process and represent a treatment target in many tumours including gliomas." (PMID 19292920, 2009). "They showed that miR-139-5p was down-regulated in glioma tissues in comparison to healthy brain tissue, and that forced expression of miR-139-5p led to down-regulation of Flt1 by direct binding of miR-139-5p to the 3′UTR of Flt1." (PMID 34646821, 2021). "The importance of VEGF and its receptors Flt1 and Flk1, along with ERK1/2 and MMP2 in glioma angiogenesis and the inhibitory effects of GLA on these proteins' expression suggested the possibility that angiogenesis could be modified in the GLA-treated tumours." (PMID 19292920, 2009).
glioblastoma (38 papers, 2009 to 2025). The most malignant astrocytic tumor (WHO grade IV). "Expression of FLT1 has been linked to sunitinib response in an in vitro model of glioblastoma." (PMID 38999991, 2024). "An early report showed an anti-tumor effect on an orthotopic glioblastoma model U87, in combination with the Flt-1/Fc chimera, and more recent evaluation of adaphostin activity in glioblastoma cell lines identified a high level of HMOX1 induction." (PMID 20618971, 2010). "The VEGF receptors, VEGFR-1 (flt-1) and VEGFR-2 (KDR), are commonly present on endothelial cells and have also been identified in human glioblastoma cells." (PMID 22295207, 2011).
colorectal cancer (36 papers, 2006 to 2024). A primary or metastatic malignant neoplasm that affects the colon or rectum. "FLT1 is a gene that regulates angiogenesis, its expression is upregulated in colorectal cancer, and it is associated with poor prognosis of patients, which is consistent with our results." (PMID 36950136, 2023). "The FLT1/VEGFR1 gene is overexpressed in colorectal cancers and is associated with poor prognosis, whereas in a minimal number of appendiceal cancers, it carries mutations, the nature of which is not specified." (PMID 37509254, 2023). "Previously, we reported that FLT1 SNPs were significantly associated with the hazard of dying of colorectal cancer after diagnosis with colon cancer and KDR SNPs were associated significantly with colorectal deaths after diagnosis with rectal cancer." (PMID 25541970, 2014). "Our results demonstrated that high Flt-1 expression in colorectal cancer cells increased their invasive ability, and is associated with poor prognosis." (PMID 23799978, 2013). "Upregulated in colorectal cancer, FLT1 promotes epithelial-mesenchymal transition (EMT), enhancing invasiveness." (PMID 38576019, 2024). "In fact, FLT-1 was found to be overly expressed in colorectal cancer tissue samples, and its activation was highly correlated to angiogenesis." (PMID 37624039, 2023). "PIGF/Flt-1 signalling is integral in colorectal cancer progression through increasing the phosphorylation of p38 MAPK, thereby upregulating MMP9 expression; resulting in increasing cellular migration/invasion." (PMID 35154142, 2022). "FLT1 has been proved to be highly expressed in nodal metastases and primary tumors of colorectal cancer, whose overexpression leads to local recurrence and lymphovascular invasion." (PMID 31383782, 2019). "These genes, including HIF1-α, VEGF receptors Flt1 and KDR, and VEGFC, suggest an association of FJX1 and angiogenic gene expression in human colorectal cancer tumor samples." (PMID 23922772, 2013). "To elucidate this discrepancy, we checked the PlGF major receptor-Flt-1 status of four different colorectal cancer cell lines, and found that Flt-1 was barely detectable in both HCT116 and HT29 cell lines." (PMID 23799978, 2013). "Here we provide evidence that, in addition to the angiogenesis, PlGF/Flt-1 signaling in colorectal cancer cells can promote CRC invasion through a p38-MMP9 pathway and the association with the poor prognosis of CRC patients was validated by two different CRC cohorts." (PMID 23799978, 2013). "Vascular endothelial growth factor (VEGFA) and its receptors 1 fms-related tyrosine kinase 1 (FLT1) and kinase insert domain receptor (KDR) have been newly recognized as critical regulators of angiogenesis and inflammation in colorectal cancer." (PMID 31383782, 2019). "Here, we showed that in clinically obtained colorectal carcinoma (CRC) specimens, Flt-1, the type 1 receptor for vascular endothelial growth factor A, was significantly upregulated." (PMID 29100318, 2017). "To investigate the clinical significance of this in vitro finding, we checked PlGF, Flt-1, and MMP9 expression in 80 human colorectal cancer tissues at the message level." (PMID 23799978, 2013).